CDKN2A (cyclin dependent kinase inhibitor 2A)
Diseases named in the same sentence as CDKN2A in open-access papers (continued):
Sharing a sentence is not in itself a finding about the gene and the disease.
tumor (continued). "The frequent genomic alterations in CDKN2A and CCND1 in HPV− clinical HNSCC cases suggest that there is a strong rationale to target CDK4/6 to inhibit tumor progression in HNSCC." (PMID 38954773, 2024). "This boundary is adjacent to the TADs containing the cancer genes CDKN2A, CDKN2B, and MTAP, all of which are tumor suppressors, and this boundary is located within a fragile site region (FRA9C)." (PMID 38758740, 2024). "Alternatively, DCISionRT combines immunohistochemical staining and scoring of COX2, FOXA1, HER2, Ki-67, p16/CDKN2A, PR, and SIAH2 in addition to clinical characteristics (age, tumor size, margin status, and palpability)." (PMID 39716322, 2024). "Among these genes, CDKN2A, CDKN2B, CUX1, LRP1B and PTPRD were retrieved as tumor suppressors from the TSGene database." (PMID 38831459, 2024). "Research suggests that certain factors, such as CDKN2A ALT, confers a cold tumor immune microenvironment and influence the immune response to immunotherapy." (PMID 38822443, 2024). "The CDKN2A ALT was also positively correlated with ORRs to ICIs and with decreased anti-tumor immunity." (PMID 38822443, 2024). "The aim of the study was to evaluate promoter methylation of CDKN1, CDKN2A, MYC, Smad3, SP1, and UBC genes in tumor tissue of HNSCC patients." (PMID 38540340, 2024). "To further explore the connection between the CDKN2A gene expression and tumor immunotherapy, we used the TIDE database to simulate the immune escape mechanism of tumor tissues and predict the response to immunotherapy." (PMID 37950153, 2023). "The Tempus RNA-Seq Report, which provides information about mRNA expression levels in a tumor sample, revealed overexpression of CCND1 and under-expression of CDKN2A." (PMID 37427132, 2023). "The expression levels of CDKN2A were upregulated whereas GAP43, CPT2 and NRG1 were downregulated in tumor tissues of CRC patients." (PMID 37205121, 2023). "Gene expression profiling showed that SLC31A1, LIPT2, CDKN2A, and GCSH expression was increased in tumor tissues, while NFE2L2, NLRP3, ATP7A, DLD, MTF1, and DLST expression was decreased in tumor tissues compared with normal tissues." (PMID 37065485, 2023). "At the same time, Cheng established a clinical prediction model from 295 NFPA tumor samples and found that three proteins, CDKN2A/p16, WIF1, TGF-β, tumor age and volume, and two clinical features were significantly associated with the recurrence of NFPA." (PMID 37780610, 2023). "Nine CRGs were differentially expressed between tumor and normal tissues, among which NFE2L2, SLC31A1, FDX1, DLD, DLAT, and DLST were lowly expressed in tumor tissues, and ATP7B, CDKN2A, and GCSH were highly expressed in tumor tissues (p<0.05)." (PMID 37205181, 2023). "CDKN2A, GEMIN2, DLAT, and ZCRB1 were expressed at higher levels in tumors than in normal tissues, while the expression of KLF9 in tumor tissue was lower." (PMID 36909185, 2023). "Genes such as ARF1, SLC25A5, and CDKN2A were significantly up-regulated in tumor samples, while genes such as SNCA, PRNP, and GLS were significantly down-regulated in tumor samples." (PMID 36980514, 2023).
tumor (continued). "For instance, the cyclin-dependent kinase inhibitors (CDKs), CDKN1A (p21Cip1), CDKN1B (p27Kip1), and CDKN2A (p16Ink4A), reprimo (RPRM), stratifin (SFN), and CDK1 are all frequently hypermethylated and play various roles in tumor radioresistance." (PMID 37455903, 2023). "Difference analyses showed that 7 of 10 CRGs were dys-regulated in tumor samples compared with those in normal samples, among which LIPT1, PDHA1, GLS and CDKN2A were up-regulated, and FDX1, DLD and MTF1 were down-regulated." (PMID 37333810, 2023). "The results showed that CDKN2A and PLK1 were significantly overexpressed in tumor samples compared to normal samples across the 18 cancer types." (PMID 37000317, 2023). "Of note, seven out of ten pivotal CRGs, which were identified in Science article, showed significantly altered expression patterns, with CDKN2A exhibited higher and DLAT, DLD, FDX1, LIAS, MTF1, PDHB exhibited lower expression in tumor tissues (P<0.05)." (PMID 37384293, 2023). "Out of these 5 hub genes, only CCND1 have high median mRNA expression in normal patients than primary tumor whereas AXL, CDKN2A, TERT, and EZH2 have high expression in the primary tumor." (PMID 36715825, 2023). "The frequency of CCNE1 amplification, MYC amplification, CDKN2A deletion, and PTEN deletion was higher in CSF than in primary tumor tissues." (PMID 37131253, 2023). "The deleted regions contained the tumour suppressors CDKN2C, SDHB, and SFPQ in 1p and CDKN2A in 9p in metastatic samples and the tumour suppressors BCL10 and NOTCH2 and the oncogenes JAK1 and NRAS in 1p in the non‐metastatic sample group." (PMID 37622176, 2023). "The gene P16INK4a, also known as cyclin-dependent kinase inhibitor 2A (CDKN2A), is a critical tumor suppressor gene." (PMID 38001653, 2023). "Further, the prognostic performance of immune subtype is superior to that of traditional tumor markers (VHL, AHNAK2, and CDKN2A) in ccRCC patients." (PMID 37315301, 2023). "Gli-related genes, including CDKN2A/p16/INK4A, Myc, and CDK2, by promoting androgen-independent tumor cell growth, lead to biochemical and tumor recurrence and lead to tumor recurrence." (PMID 37175453, 2023). "Among them, the expression levels of CDKN2A, GLS and LIPT1 were significantly upregulated whereas the expression levels of DLAT, DLD, FDX1, MTF1 was significantly downregulated in tumor samples." (PMID 37072493, 2023). "The models showed characteristic copy number variations (CNV) of disease-related genes (e.g., MDM4, EGFR, CDKN2A, CDK4, and MDM2) that were fairly consistent with the primary tumor." (PMID 37508520, 2023). "Observing the expression pattern among all major cell types, the expression of CDKN2A and CCL20 are highly correlated and ubiquitous to malignant ductal 2, suggesting the key role of senescent tumor cells as secretor of CCL20 in the tumor TME." (PMID 37398643, 2023).
tumor (continued). "The expression of COX11, COX17, LIAS, CDKN2A and AOC3 was significantly higher in tumor tissues than in normal tissues." (PMID 38078879, 2023). "Two of these regions are most frequently altered, namely, the CDKN2A–ARF gene at 9p21 and NF2 at 22q12, which behave as tumor suppressors." (PMID 36834912, 2023). "This aberration mainly results in the silencing of genes that contribute to DNA repair and tumour suppression, such as MLH1, CDKN2A, and SFRP2, hence promoting cancer growth and survival." (PMID 37953923, 2023). "Recent molecular biological studies have revealed frequent genetic alterations in three tumor suppressor genes, neurofibromatosis 2 (NF2), cyclin-dependent kinase inhibitor 2 A (CDKN2A, p16), and BAP1 in MMe." (PMID 37479714, 2023). "Our results show that the frequency of inactivating CDKN2A/RB1 alterations is highest after tumor progression following post-operative combination therapy, and PDGFRA/MET alterations co-appear with CDKN2A inactivation." (PMID 37932833, 2023). "Modification of H3K27me3 in the promoter region of the CDKN2A-2B gene cluster and enrichment of EZH2 were reduced, which increased mRNA levels of the tumor-suppressor genes P14, P15, and P16 and inhibited HCC cell proliferation and migration." (PMID 37268997, 2023). "Suppression of ACTR5 activated CDKN2A expression, ablated CDK/E2F-driven cell cycle signaling, and attenuated HCC tumor growth." (PMID 36563143, 2022). "Hsa-mir-124-3p, a downregulated miRNA predicted to bind to CDKN2A, is considered a key miRNA in CCRCC, inhibiting tumor migration, invasion, and proliferation." (PMID 36531222, 2022). "The simultaneous deletions of CDKN2A and CDKN2B is frequently identified across many tumour types as a consequence of homozygous 9p21.3 deletions involving the CDKN2A/p14ARF/CDKN2B loci." (PMID 35324914, 2022). "Numerous genes that inhibit tumour growth, such as CDKN2B, CDKN2A, CDH1, DAPK1, SOCS1, and SHP1, were rendered inactive as a result of DNA hypermethylation at the CpG islands that are associated with their promoters." (PMID 36359286, 2022). "It is possible that in LMS tumors with high accumulation of DNA damage, disruption of cell cycle checkpoint regulation through RB1, CDKN2A/B, MYC, FBXW7, or NF1 is necessary to maintain the viability of the tumor." (PMID 35468996, 2022). "Transcriptions of CDKN2A, CDKN2B, CDKN2B_AS1, and MTAP were included because these genes are located at 9p21.3, and they are also potential tumor suppressors." (PMID 36313281, 2022). "CDKN2A, GLS, LIPT1, and PDHA1 were up-regulated in tumor samples, and FDX1, DLD, MTF1 were down-regulated in tumor samples." (PMID 36176287, 2022). "(III) Induced pluripotent stem cells can be engineered as cancer-specific cells by targeting tumor suppressors such as SMAD4, Rb/P16, BRCA1, CDKN1A, and CDKN2A." (PMID 35992863, 2022). "We found that LIAS and CDKN2A were significantly upregulated in tumor samples, and FDX1, DLD, DLAT, PDHA1, PDHB, MTF1, and GLS were significantly downregulated in tumor samples." (PMID 36531222, 2022). "To explore the prognostic mechanism of CDKN2A/BHD in LUAD, we first analyzed common clinical characteristics including age, gender, smoking history, and tumor stage." (PMID 35253368, 2022). "TCGA-confirmed tumor suppressor genes with a lower copy number in the two cells included RB1 and CDKN2A/B." (PMID 36430324, 2022).
tumor (continued). "Other genomic alterations identified in this patient were EGFR A1118T, which was not an actionable driver, and CDKN2A/B loss, which was a variant of unknown significance; microsatellite status was stable, and tumor mutation burden was low (three mutations per megabase)." (PMID 35962206, 2022). "In total, 8 (80%) CID genes showed differential expression, CDKN2A showed significant upregulation, and seven CID genes showed significant downregulation in the tumor samples (p < 0.05, one-sided Wilcoxon rank-sum test)." (PMID 36263424, 2022). "To further explore how the co‐deletion of IFN‐I influences outcomes in CDKN2A/BHD LUAD, we examined the tumor immune microenvironment by performing an immunity estimation of 25 gene sets associated with innate and adaptive immunity." (PMID 35253368, 2022). "CDKN2A mRNA was upregulated in TCGA CIMP-RCC in comparison to normal tissues, as it was for all the RCC tumor subtypes." (PMID 36455002, 2022). "Alterations of BAP1 (70 %), CDKN2A (96 %), and NF2 (67 %) were detected at a higher frequency than reported for tumor biopsies." (PMID 36077838, 2022). "Estimated common deletion regions (CDRs) were observed in many tumor suppressor genes, such as ATM, CDKN2A, FAT1, miR31HG, PTEN, and RB1, in the SNP array-based COSMIC datasets." (PMID 36531022, 2022). "In this study, CDKN2A was positively correlated with the infiltration of activated B and CD4 T cells in the tumour microenvironment, leading to a better prognosis of HNSCC." (PMID 36699463, 2022). "P16, also known as cyclin-dependent kinase inhibitor 2A (CDKN2A), is an important tumor suppressor gene that plays an essential role in cell cycle regulation by inhibiting the G1 phase of cells from entering the S phase." (PMID 35813225, 2022). "Moreover, although MTAP/CDKN2AMUT RCC may be insensitive to targeted therapy, the high degree of tumor heterogeneity and higher PD-L1 and CXCL13 expression characterizations reflected that MTAP/CDKN2A-deficient features could benefit from immunotherapy for patients with RCC." (PMID 35979371, 2022). "The data indicated that CDKN2A, TTC39C, and PKIB exerted critical functions in modulating tumor immunity of LUAD." (PMID 35832557, 2022). "Significant focal copy number changes as identified by GISTIC analysis (q-value of < 0.001) occurred on chromosomes 3, 9, 16 and 22 in regions that contain tumour suppressor genes, BAP1 (chr3), CDKN2A (chr9) and NF2 (chr22)." (PMID 35637530, 2022). "Subsequently, we detected the expression of these CRGs in tumor and normal samples and found that 6 genes, FDX1, LIAS, DLD, DLAT, PDHB and MTF1, were significantly downregulated in tumors, while 2 genes, GLS and CDKN2A, were significantly upregulated." (PMID 36246586, 2022). "To evaluate the impact of tumor cell–intrinsic PRC2 inactivation on the TME in vivo, we generated a histologically confirmed Nf1–/– Cdkn2a/b–/– murine MPNST tumor–derived cell line (SKP605) from skin-derived precursors (SKPs) of C57BL/6J mice." (PMID 35852856, 2022). "ATP7B, CDKN2A, FDX1, and SLC31A1 had the lowest expression in tumor cell-enriched region (PanCK-expressing)." (PMID 36618352, 2022).
tumor (continued). "Focally deleted regions identified the tumour-suppressor genes RHOA at 3p21, CDKN2A and CDKN2B at 9p21, RAD51B, MAX, DICER1, BCL11B, NKX2-1, CCNB1IP1 and BAZ1A at 9q33." (PMID 34980126, 2022). "Transcript levels of β-catenin target proteins such as Ccnd2, CDKN2A, and BIRC5 are known to be increased in tumor patients." (PMID 36209344, 2022). "Especially for LUSC, a comprehensive study of 178 LUSC specimens revealed that significant alteration in CDKN2A and RB1 gene was identified in 72% of LUSC cases, and CDK4/6 gene was frequently amplified in CDKN2A intact tumor." (PMID 36005200, 2022). "However, although CM has a much higher CDKN2A loss than MM, MM tends to show a greater frequency of CCND1 and CDK4 amplification, implying CDK4 blocking agents may achieve a desired anti-tumor effect on MM." (PMID 34350118, 2021). "Mounting evidence implicates the role of the INK4A/ARF (originally called CDKN2A) gene locus and retinoblastoma 1 (RB1) tumor suppressor pathway in pNET pathogenesis." (PMID 34680266, 2021). "The sensitivity of detecting Ta tumor was also superior to the reported methylation assays by DLX1 and ITGA4 (50.0–84.6%) and BCL2, CDKN2A and NID2 (61.1%)." (PMID 33902700, 2021). "Consistent with this idea, upon grouping the DepMap cancer cell lines according to tissue origin, we noted that CDKN2A status and TYMP expression have varying effects on controlling TYMS dependency in different tumor types." (PMID 34454516, 2021). "While only subtle changes (vs. wild type) were observed in mRNA expression of CDKN2A/MTAP in 9p21-LOH tumors, homologous deletion of the genes in tumor cells led to a marked decrease in their mean gene expression levels in bulk tumor tissues." (PMID 34556668, 2021). "Common mutations in this context involve, for example, the activation of oncogenes, such as BRAF and RAS and the inactivation of key tumor suppressors, such as PTEN and CDKN2A." (PMID 34831311, 2021). "The CDKN2A locus which is found on human chromosome 9p21 encodes two overlapping transcripts that produce two different proteins, p16INK4a and p14ARF (ARF), both of which are established tumor suppressors." (PMID 33445626, 2021). "These alterations are already found in early precursor lesions such as PanIN, following inactivation of tumor suppressor genes such as CDKN2A, TP53m or SMAD4, which in turn contribute to an enhancement of the tumor stroma." (PMID 34944807, 2021).